MSH5 (mutS homolog 5)
Description:
Involved in DNA mismatch repair and meiotic recombination processes. Facilitates crossovers between homologs during meiosis (By similarity).
Synonyms: G7; MUTSH5; NG23; POF13; SPGF74
Tractability: PROTAC: ubiquitination databases record sites on it.
Safety:
Unwanted effects reported when the protein is acted on. In parentheses: how it was acted on, where the effect was seen, and who reports it.
thrombocytopenia (source: ClinPGx)
Gene: Protein-coding gene on chromosome 6 (31,739,677 to 31,762,676, forward strand). Ensembl gene ENSG00000204410.
Subcellular location (Human Protein Atlas): Nucleoli fibrillar center
Pathways (Reactome):
Reproduction: Meiotic recombination
Gene Ontology:
Molecular function: protein binding; ATP binding; ATP-dependent DNA damage sensor activity; mismatched DNA binding
Biological process: reciprocal meiotic recombination; meiosis I; mismatch repair
Cellular component: DNA repair complex
Genetic constraint (gnomAD): Loss-of-function variants: 78 observed, 111.11 expected, observed/expected ratio (o/e) 0.7, 90% interval 0.58 to 0.85. The synonymous counts are far from expectation, so gnomAD's model fits this gene poorly and the ratio says little. Missense variants: 889 observed, 1,079.8 expected, observed/expected ratio (o/e) 0.82, 90% interval 0.78 to 0.87. Synonymous variants: 326 observed, 412.77 expected, observed/expected ratio (o/e) 0.79, 90% interval 0.72 to 0.87.
Homologues: Orthologues: macaque MSH5 (98% identical), chimpanzee MSH5 (96% identical), pig MSH5 (92% identical), rabbit MSH5 (91% identical), mouse Msh5 (89% identical), rat Msh5 (88% identical), dog MSH5 (87% identical), guinea pig MSH5 (87% identical), tropical clawed frog msh5 (56% identical), zebrafish msh5 (50% identical), Caenorhabditis elegans msh-5 (30% identical). Paralogues in human: MSH6 (22% identical), MSH3 (22% identical), MSH4 (19% identical).
Diseases named in the same sentence as MSH5 in open-access papers:
MSH5 is named in the same sentence as 48 diseases in open-access papers, as found by Europe PMC text mining. Sharing a sentence is not in itself a finding about the gene and the disease. The quoted sentences say what the papers report.
lung carcinoma (10 papers, 2012 to 2020). "Another non-significant positive association for NHL, especially with DLBCL, was with a lung cancer susceptibility variant, rs3131379, in MSH5 or mutS homolog 5, a gene involved in the DNA mismatch repair pathway." (PMID 24598796, 2014). "In addition, mutations in MMR genes, particularly those in MSH3 and MSH5, may be associated with the risk of lung cancer and even lead to increased alkylation tolerance." (PMID 28093084, 2017). "Our findings on MSH5 and MHC variants indicate possible involvement of variants in or near this highly-conserved immune-regulatory region in the etiology of NHL (including FL and DLBCL), in addition to that of lung cancer." (PMID 24598796, 2014). "The same applies to another three genes KLF6 (Krüppel-like zinc finger transcription factor), MSH5 (MutS protein homolog 5) and ACTA2 (Alpha-smooth muscle actin), which were also found to be associated with lung cancer by several previous GWASs, albeit not as prominently as CHRNA5 and TERT." (PMID 27323854, 2016). "Given wide-stretched linkage disequilibrium to the area APOM/BAG6/MSH5, there is currently simply not enough information or evidence to conclude whether the potential pleiotropy of lung cancer and systemic lupus erythematosus is spurious, biological, or mediated." (PMID 28273134, 2017).
Infertility (9 papers, 2012 to 2025). "The construction of a homozygous Msh5-mutated male mouse model demonstrates complete infertility, consistent with the phenotypes of patients with NOA." (PMID 41280724, 2025). "Our study provides further supporting evidence on the pathogenicity of MSH5 mutation in male infertility, improving the future genetic diagnosis of infertile individuals in clinic." (PMID 35742973, 2022). "Up to now, several variants in MSH4 and MSH5 have been reported in infertile men and women." (PMID 35742973, 2022). "In the Msh5-/- female mice, meiosis is arrested due to the disruption of chromosome pairing at prophase I, subsequently, resulting in progressive loss of oocytes and infertility." (PMID 28175301, 2017). "Therefore, our study demonstrates that the MSH5 c.1126del could cause meiotic recombination failure and lead to human infertility, improving the genetic diagnosis of NOA clinically." (PMID 35742973, 2022). "Among these mutated infertility genes, mutations of FSIP2, CFAP69, CEP19, MSH5 or MCM8 are recessive for spermatogenic failure or premature ovarian insufficiency." (PMID 35547809, 2022). "In our study, the Msh5D486Y/D486Y mice were infertile with atrophic ovaries, confirmed the adverse effect of human MSH5 p.D487Y on oogenesis." (PMID 28175301, 2017). "Msh4 or Msh5 knockout mice, while able to initiate meiosis normally, are unable to stabilise intermediates in the HR process and ensure proper chromosome pairing, ultimately leading to a reduced number of oocytes and signs of ovarian failure and infertility in mice." (PMID 37430352, 2023).
Premature ovarian insufficiency (5 papers, 2022 to 2026). Amenorrhea due to loss of ovarian function before the age of 40. "LncRNA HCP5 helps YBX1 nuclear localization and promotes MSH5 transcription and DNA damage repair in granulosa cells from patients with premature ovarian insufficiency." (PMID 41507135, 2026). "For example, it has been reported that HCP5 regulates premature ovarian insufficiency through transcriptionally modulating MSH5 to mediate DNA damage repair by YB1." (PMID 35602292, 2022). "Recent studies identifying factors responsible for primary and premature ovarian insufficiency (POI) have reported either dramatic downregulation or non-functional variants of several DDR pathway members, such as BRCA1, RAD51, ATR, MSH4, MSH5, and FANC genes." (PMID 40148269, 2025).
colorectal cancer (4 papers, 2009 to 2022). A primary or metastatic malignant neoplasm that affects the colon or rectum. "Another gene related to colorectal cancer segregating (in one family) was MSH5, but, despite having a deleterious score and segregating, the patients had no microsatellites instability and adding the lack of scientific information available for this variant, it remained with unknown significance." (PMID 35181726, 2022).
Autoimmunity (3 papers, 2022 to 2023). The occurrence of an immune reaction against the organism's own cells or tissues. "CYP21A2, as well as MSH5, PPP1R18, and NEU1 have been demonstrated by previous GWASs associated with other autoimmune disorders such as RA, ankylosing spondylitis (AS), T1DM, and SLE." (PMID 37197658, 2023). "In the current study, we also observed a significantly higher frequency of the rs3130484 SNP in T1D patients (35.5%) than in controls (17.8%, OR = 2.54 (1.77–3.66), p = 3.01 × 10−7) that could suggest that the SNP located within the MSH5 gene might affect autoimmunity development both in CD and T1D." (PMID 35456320, 2022).
Fanconi anemia (3 papers, 2016 to 2020). Fanconi anemia (FA) is a hereditary DNA repair disorder characterized by progressive pancytopenia with bone marrow failure, variable congenital malformations and predisposition to develop hematological or solid tumors. "In particular, relying on functional partners of CORIN and MSH5, several additional pathways were involved, including mismatch repair pathway, meiotic recombination pathway, and Fanconi anemia pathway." (PMID 32724329, 2020).
primary ovarian insufficiency (3 papers, 2012 to 2023). "In addition, a case-control study including 41 women with premature ovarian failure and 39 controls suggested that there is a correlation between the MSH5 Pro29Ser polymorphism and premature ovarian failure in women." (PMID 22594646, 2012).
Azoospermia (2 papers, 2012 to 2022). Absence of any measurable level of sperm,whereby spermatozoa cannot be observed even after centrifugation of the semen pellet. "One intronic SNP in MLH1 (rs4647269) and two non-synonymous SNPs in PMS2 (rs1059060, Ser775Asn) and MSH5 (rs2075789, Pro29Ser) seem to be risk factors for the development of azoospermia or oligozoospermia." (PMID 22594646, 2012). "By analyzing the relationship between these genes and phenotype, we speculated that case 1 showed azoospermia, which may have been related to the disruption of the MSH5 or/and ZMYND15 gene." (PMID 36626513, 2022).
common variable immunodeficiency (2 papers, 2009 to 2010). "Increased microhomology at the CSR junctions has also been observed in mice deficient in PMS2, MLH1, MSH4 or MSH5 and in IgAD and common variable immunodeficiency (CVID) patients carrying mutations in the MSH5 gene." (PMID 19008195, 2009).
glioblastoma (2 papers, 2023 to 2025). The most malignant astrocytic tumor (WHO grade IV). "We replicated most of these associations in glioblastoma (Klughammer cohort) where 14 of 17 genes were also positively associated with TERT expression, including four genes related to DNA repair (XRCC2, MSH5, TRAIP, BRIP1)." (PMID 37418389, 2023). "Hypermethylation of the MSH5 gene has been investigated in recurrent glioblastoma." (PMID 40640872, 2025).
glioma (2 papers, 2020 to 2021). A benign or malignant brain and spinal cord tumor that arises from glial cells (astrocytes, oligodendrocytes, ependymal cells). "We found a higher MSH5 expression in gliomas of WHO grades II/III and IV." (PMID 34341417, 2021). "Further studies with a panel using more IHC markers, such as Atm, Msh4, Msh5, or other proteins which may be altered in hypermutated gliomas, could potentially improve the sensitivity further." (PMID 32051040, 2020).
male infertility (2 papers, 2022 to 2023). The inability of the male to effect fertilization of an ovum after a specified period of unprotected intercourse. "But it was also described as a new gene in the context of male infertility, since previous studies showed that mutations in gene involved in recombination such as MSH5 gene cause meiotic arrest at stage IV of the spermatogenic cycle." (PMID 37556504, 2023). "This MSH5 variant was verified by Sanger sequencing and was confirmed to co-segregate with male infertility in this family." (PMID 35742973, 2022). "Variants in MSH5 are associated with human primary ovarian insufficiency and male infertility." (PMID 35742973, 2022). "Therefore, we suggest that the identified homozygous MSH5 c.1126del could be pathogenic for male infertility in this pedigree." (PMID 35742973, 2022).
ovarian failure (2 papers, 2010 to 2026). "In contrast to other critical genes during meiosis, such as Dmc1, Msh5, Spo11 and Atm that cause early ovarian failure due to rapid loss of oocytes following disruption of meiosis I, Hormad1 deficiency does not activate apoptotic pathways and does not lead to gross premature loss of oocytes." (PMID 21079677, 2010).
squamous cell carcinoma (2 papers, 2017 to 2020). A carcinoma arising from squamous epithelial cells. "Moreover, among MSH5 rs707939 T allele carriers, stratification analysis showed that male patients, patients ≤55 years old, smokers, and patients diagnosed with squamous cell carcinoma faced a lower risk of overall severe toxicity than their counterparts." (PMID 28093084, 2017). "For MSH5 rs707938, patients with squamous cell carcinoma carrying TT or TC had longer OS." (PMID 32742474, 2020).
brain tumour (1 paper, 2021). "MSH5 is primarily involved in meiosis, therefore the impact of these hypoxia-induced changes in brain tumour cell lines is debatable." (PMID 33986995, 2021).
cervical carcinoma (1 paper, 2016). A carcinoma arising from either the exocervical squamous epithelium or the endocervical glandular epithelium. "The same was found when the DNA repair candidate genes from cervical carcinoma (MSH5, OGG1) and lung squamous cell carcinoma (CHEK1) were analyzed." (PMID 27683114, 2016).
Lynch syndrome (1 paper, 2018). An autosomal dominant hereditary neoplastic syndrome characterized by the development of colorectal carcinoma and a high risk of developing endometrial carcinoma, gastric carcinoma, ovarian carcinoma, renal pelvis carcinoma, and small intestinal carcinoma. "While MSH5 is not known to be a Lynch syndrome gene, we included this individual in further analyses of MMR germline:somatic alteration carriers." (PMID 30217226, 2018).
small cell lung carcinoma (1 paper, 2022). Small cell lung cancer (SCLC) is a highly aggressive malignant neoplasm, accounting for 10-15% of lung cancer cases, characterized byrapid growth, and early metastasis. "However, inactivation of MMR genes like MSH3 and MSH5 by methylation and single nucleotide polymorphisms (SNPs) has been associated with increased sensitivity to cisplatin-based chemotherapy in small cell lung carcinoma (J.-Y." (PMID 36076047, 2022).
sterility (1 paper, 2006). "Msh5 codes for a member of the mismatch repair family of proteins, that is expressed mainly in gonads and has a role in chromosome pairing during meiosis; deficiency was associated with apoptosis of testicular and ovarian cells and sterility." (PMID 17183687, 2006).
viral infection (1 paper, 2022). "A deletion between Msh5 and 1700031A10Rik at the 4th month formed Msh5-1700031A10Rik out-of-frame fusion; Samd9 is a tumor suppressor involving in cell proliferation and innate immune response to viral infection." (PMID 35869059, 2022).
tumor (14 papers, 2013 to 2025). "For example, there is evidence that methylation of genes involved in mismatch repair, including MSH5, is associated with altered therapeutic response, with hypermethylation potentially impeding DNA repair functions and facilitating tumor progression." (PMID 40640872, 2025). "MSH5, one of the most frequently contacted genes, encodes a MutS homolog, which is involved in homologous chromosome recombination and has been linked to DNA damage response and repair, neoplasia and immunity." (PMID 34341417, 2021). "We identified eight overexpressed and mutated tumor antigens with poor prognostic value of PRAD, including KLHL17, CPT1B, IQGAP3, LIME1, YJEFN3, KIAA1529, MSH5 and CELSR3." (PMID 34872584, 2021). "There are only a few SNPs in MSH5 with significant implications in the neoplasia." (PMID 32756484, 2020). "Tumor-suppressor genes BAX, CDKN2A, and MSH5 were negatively correlated with LEPROT in multiple cancer types, and most tumor-suppressor genes were suggested to be positively correlated with LEPROT in a gene-consistent way across cancer types." (PMID 34804118, 2021).
cancer (11 papers, 2009 to 2022). A tumor composed of atypical neoplastic, often pleomorphic cells that invade other tissues. "SNPs in MSH5 are associated with fewer types of cancer, probably due to lack of relevant studies on this gene." (PMID 32756484, 2020).
infection (2 papers, 2017 to 2022). The state of being infected such as from the introduction of a foreign agent such as serum, vaccine, antigenic substance or organism.
MSH5 also shares sentences with these, for which no sentence is quoted: celiac disease (2 papers); immune diseases (2); systemic lupus erythematosus (2); testicular cancer (2); ankylosing spondylitis (1); breast carcinoma (1); Cirrhosis (1); diabetes (1); female infertility (1); hematologic disorder (1); immune deficiency (1); Kawasaki disease (1); lung squamous cell carcinoma (1); meningioma (1); migraine (1); Neurologic disorder (1); Oral ulcer (1); osteosarcoma (1); prostate carcinoma (1); Recurrent infections (1); serous ovarian cancers (1); spermatogenic failure (1); T-cell ALL (1); testicular tumors (1); Type 1 Diabetes (1).